GSDMB (gasdermin B)
Diseases named in the same sentence as GSDMB in open-access papers (continued):
Sharing a sentence is not in itself a finding about the gene and the disease.
cancer (continued). "Finally, our results provide a new and accessible therapeutic approach for HER2/GSDMB + cancers with adverse clinical outcome." (PMID 36163066, 2022). "GSDMB is located in a genomic region that is frequently amplified during cancer development." (PMID 35954405, 2022). "In this sense, our R26-GB2 model can be useful in future studies to assess whether GSDMB regulates specific genes in particular tissues/cell types from both healthy and cancer conditions." (PMID 35281099, 2022). "Specifically, in cancer cells xenografted in immunocompetent mice, the GSDMB intrinsic pyroptotic function could be activated via immunocyte-derived Granzyme A (GZMA)." (PMID 35281099, 2022). "Accumulated evidence indicates that GSDMB is overexpressed in several cancer types and may be involved in cancer progression and metastasis." (PMID 34568046, 2021). "All of the results above indicate that GSDMB could be a potential valuable biomarker or possible target in cancer treatment." (PMID 34957313, 2021). "However, the specific functions of GSDMB in carcinogenesis, cancer metastasis, and progression are unclear." (PMID 34858408, 2021). "GSDMB is often expressed in cancer cells derived from these tissues, whereas it may be silenced in esophageal and gastric cancer cells." (PMID 33406603, 2021). "Taken together, these findings not only demonstrated that GSDMB-mediated pyroptosis acts downstream of GzmA but that cytotoxic lymphocytes may deliver GzmA into GSDMB-expressing cancer cells to facilitate antitumor immunity." (PMID 34429144, 2021). "GSDMB is a member of the gasdermin gene family and expressed in various types of cancer." (PMID 34368222, 2021). "Although GSDMB resulted dysregulated in a variety of cancers, the exact function of this protein is still largely unknown." (PMID 28272342, 2017). "Interestingly, variations in the expression of trans-acting factors, such as SR proteins and hnRNPs, were found also in cancer, in which a differential expression of GSDMB splicing isoforms was repeatedly evidenced." (PMID 28272342, 2017). "At least four splicing isoforms of GSDMB have been identified, which may play differential roles in cancer." (PMID 24675552, 2014). "Gasdermin B (GSDM B), a member of the gasdermin protein family, is involved in the regulation of inflammatory processes and the immune response, and its expression may be associated with cancer development and progression." (PMID 42074184, 2026). "This review consolidates current insights into GSDMB’s structure, functions, and clinical relevance, offering a valuable resource to advance research and therapeutic development, particularly as GSDMB emerges as a promising target in cancer and immune disorders." (PMID 40452932, 2025). "Therefore, the important role of GSDMB in cancer cell pyroptosis remains elusive." (PMID 39062587, 2024). "GSDMB in full-length or in cleavage may have different effects on cancer progression." (PMID 38711020, 2024). "However, the relationship between GSDMB and the cancer immune microenvironment is unclear." (PMID 38711020, 2024). "Therefore, combining anti-HER2 agents like trastuzumab with chloroquine may enhance therapeutic outcomes in cancers exhibiting both GSDMB and HER2 positivity." (PMID 38304430, 2024). "In 2020, Zhou and colleagues reported that granzyme A (GzmA) derived from natural killer (NK) and/or CD8+ T cells cleaved GSDMB at K244 (major cleavage site) and K229 (minor cleavage site), which was conserved in GSDMBiso1-4 in a colon cancer cell line, resulting in pyroptosis in cancer cells." (PMID 37781519, 2023). "Given that these tumors were treated, the association observed between GSDMB/LC3B/Rab7 staining patterns and clinical behavior support the idea that GSDMB over-expression could promote protective autophagic response to therapy in HER2 positive cancer patients." (PMID 36163066, 2022). "In addition to the effect of GSDMB on cancer, our study offers other interesting results." (PMID 35281099, 2022).
cancer (continued). "Therefore, a more in-depth study on the role of GSDMB in pyroptosis and cancers are required." (PMID 36189207, 2022). "Besides it, it also has been reported that GZMA can cleave GSDMB in murine cancer cells recently." (PMID 36119049, 2022). "In addition, it was recently found that the serine protease granzyme A (GZMA) in cytotoxic lymphocytes could access target cells via perforin and evoke cancer cells to undergo pyroptosis by cleaving activated GSDMB protein, as well as activate immune response." (PMID 35847844, 2022). "In addition, these studies also indicated that cancer immunotherapy with the immune checkpoint inhibitors might be a better strategy for treating the GSDMB-positive tumors." (PMID 34421915, 2021). "In GSDMB, one of the members of the GSDM family, pyroptosis-like features have also been observed, and several studies have suggested that overexpression of GSDMB exists in multiple types of carcinomas, in which it could be correlated with the progression of cancer and metastasis." (PMID 34957313, 2021). "Strikingly, GSDMB expression is increased in cancer cells stimulated with cytokines, including interferon (IFN)-γ and tumor necrosis factor (TNF)-α, which makes us speculate that cytokine production and cytotoxic mechanisms cooperate in inducing GSDMB-mediated pyroptosis in cancer cells." (PMID 33406603, 2021). "Altogether, these data demonstrate that GSDMB overexpression is functionally involved in promoting resistance to the anti-HER2 inmunotherapy trastuzumab, and this may explain its association with adverse clinical behaviour in HER2+ cancers." (PMID 27462779, 2016). "In gastric tissue, it has been suggested that cellular and viral origin LTR promoters could selectively control GSDMB expression in normal and cancer tissues, respectively, and that an Alu element, located in the upstream region of GSDMB gene, could be also responsible for GSDMB up-regulation." (PMID 24675552, 2014). "Its 10 variations exhibit divergent protease interactions: GzmA‐cleaved GSDMB induces pyroptotic cell death in cancer cells, whereas neutrophil elastase (ELANE) cleaved GSDMB lacks pyroptotic activity." (PMID 41574659, 2026). "However, we demonstrate a promising therapeutic strategy targeting GSDMB, which may improve KIRC patient prognosis, provide an understanding of the possible underlying mechanisms of action, and provide new insights into GSDMB as a prognostic marker and potential therapeutic target for cancers." (PMID 37064151, 2023). "Gasdermin (GSDM)-mediated pyroptosis is functionally involved in multiple diseases, but Gasdermin-B (GSDMB) exhibit cell death-dependent and independent activities in several pathologies including cancer." (PMID 36899106, 2023). "Next, to investigate the potential mechanisms that GSDMB participated in the progression of cancers, we used the online tool STRING to construct a protein–protein interaction (PPI) network for GSDMB." (PMID 37064151, 2023). "Following a study, anti‐GSDMB antibody loaded into hyaluronic acid biocompatible nanocapsules has a significant and targeted impact on HER2‐positive cancers that overexpress GSDMB." (PMID 37752941, 2023). "Six GSDM family genes (i.e., GSDMA, GSDMB, GSDMC, GSDMD, GSDME, and PJVK) have long been described in other fields; however, they have been rarely investigated in a pan-cancer setting." (PMID 36003332, 2022). "Meanwhile, it has been reported that other members of the gasdermin family, like GSDMB, GSDMC also involved in the pyroptosis of cancer cells." (PMID 35756622, 2022). "In cancer, pyroptosis has been shown to be triggered by almost all signaling pathways in which GSDME, GSDMD, GSDMC, or GSDMB serve as the executors." (PMID 35673561, 2022). "GSDMB can also be upregulated by different chemokines (IFN-α, -β, and -γ, or a lesser extent TNF–α) in cancer models, and methotrexate in gut epithelium, but the effects of this upregulation depends on the cellular and pathological settings." (PMID 36163066, 2022).
cancer (continued). "GSDMB induces survival to anti-HER2 agents through the promotion of pro-survival autophagy in breast and gastric HER2 cancers." (PMID 36139701, 2022). "The GSDM family includes six members, GSDMA, GSDMB, GSDMC, GSDMD, GSDME (DFNA5), and PJVK (Pejvakin, DFNB59), which can induce pyroptosis, thereby regulating the tumorigenesis of various cancers." (PMID 36505798, 2022). "Our analysis of TGGA data demonstrated that GSDM genes (GSDMB, GSDMC, and GSDMD in particular) were upregulated in different types of cancers compared with the corresponding normal specimens." (PMID 36003332, 2022). "Thus, GSDMB might participate in cancer development and metastasis." (PMID 36163033, 2022). "GSDMB-mediated pyroptosis can function downstream of GZMA, and cytotoxic lymphocytes can transmit GZMA to GSDMB-expressing cancer cells, enhancing antitumor immunity." (PMID 35739182, 2022). "We found that most tumors analyzed and exhibited a certain level of GSDMs expression; however, the expression of GSDMD, GSDMB, and GSDME in pan-cancers was markedly higher than that of other genes." (PMID 36003332, 2022). "GSDMB is specifically cleaved by lymphocyte-derived GZMA, unleashing its pore-forming activity and inducing pyroptosis in GSDMB-expressing cancer cells." (PMID 33941231, 2021). "GSDMB is transcribed by two promoters, cellular and LTR promoters, and the latter is mainly used in normal tissues and in cancer cell lines." (PMID 26016667, 2015). "In conclusion, as a multifunctional protein, GSDMB not only participates in pyroptosis but also regulates non-pyroptotic processes, playing an important role in cancer progression and inflammatory diseases." (PMID 40452932, 2025). "As far as we know, no reports have described the clinical significance of GSDMB expression in stromal immune cells in cancer." (PMID 38711020, 2024). "Rather, serine protease granzyme A (GZMA) delivered from cytotoxic T lymphocytes and natural killer (NK) cells activates GSDMB by site-specific cleavage of the inter-domain linker, therefore liberating NTD and subsequently executing pyroptotic cell death in cancer cells." (PMID 36599845, 2023). "GSDMB, GSDMC, GSDMD, GZMB, and GSDME displayed extensive CNV amplification across cancer types." (PMID 35620284, 2022). "Gasdermines (GSDMD, GSDMA, GSDMB, and GSDME) showed hypermethylation across cancers." (PMID 36605187, 2022). "As expected, lapatinib treatment produced a significant reduction in cancer cell growth of GSDMB-silenced tumors (shGB1 and shGB2), but not in HCC1954 shNTC." (PMID 36163066, 2022). "In fact, GSDMB upregulation is functionally involved in mediating HER2 BC’s aggressive behavior in multiple ways, since it enhances cancer cell migration and invasion, in vivo tumorigenesis (in GEMMs and orthotopic xenografts), metastasis, and resistance (innate and acquired) to anti-HER2 therapies." (PMID 36139701, 2022). "GSDMB expression can also correlate with a positive or negative prognosis depending on the cancer type." (PMID 35608339, 2022). "Our results are in line with previous studies describing GSDMB, Rab7 and LC3 over-expression as poor prognosis cancer factors and reinforce the connection between GSDMB/Rab7/LC3B co-expression, protective autophagy, resistance to anti-HER2 therapies and adverse prognosis in clinical samples." (PMID 36163066, 2022). "Significantly upregulated PRGs included PYCARD in 12 cancers; GSDMB in 10 cancers; IL18 in 9 cancers; GSDMD, CASP8, GZMB, and GPX4 in 8 cancers; AIM2 and CASP6 in 7 cancers; GZMA in 6 cancers; GSDME, CASP4 and DHX9 in 5 cancers; GSDMA and GSDMC in 4 cancers." (PMID 36605187, 2022). "whereas, GSDMB and GSDME were moderately expressed in pan-cancer." (PMID 35922531, 2022). "In this article, we first revealed that the mRNA expression of GSDMB was not normal in different types of cancers." (PMID 34957313, 2021).
cancer (continued). "It has been reported that natural killer (NK) cells and cytotoxic T lymphocytes could kill cancer cells by releasing granzyme A (GZMA) to cleave GSDMB and granzyme B (GZMB) to directly cleave GSDME to activate pyroptosis in cancer cells." (PMID 34616734, 2021). "Therefore, the ability of GZMA to induce pyroptosis and kill cancer cells also depends on the expression of GSDMB, which is not expressed in some human tissues and is absent in mice." (PMID 39735183, 2024). "The analysis results show that in KIRC (rho = −0.503) and PRAD (rho = −0.378), but not in other cancers, immature dendritic cells (iDCs) may be regulated by GSDMB gene." (PMID 37064151, 2023). "We observed that NLRP7 (n = 8), AIM2 (n = 10), CASP8 (n = 6), GSDMA (n = 5), GSDMB (n = 8), and GSDMC (n = 12) mainly showed hypomethylation in most cancers, and PLCG1 (n = 11), NLRP6 (n = 13), ELANE (n = 11), CASP6 (n = 5), NLRC4 (n = 12), and PYCARD (n = 8) showed hypermethylation in most cancers." (PMID 35246158, 2022). "This targeted nanomedicine (termed AbGB-NCs) increased the sensitivity to trastuzumab in vitro, but also reduced cancer cell migration as well as in vivo breast tumor growth and lung metastasis in orthotopic xenografts, specifically in GSDMB-overexpressing cells, without systemic toxicity." (PMID 36139701, 2022). "So, whether the GZMA can kill cancer cells through pyroptosis also depends on the expression of GSDMB, which do not express in some human tissue and is absent in mouse." (PMID 35673561, 2022). "The activation of GSDMB to induce pyroptosis in some specific cancers may be a promising modality to improve the efficacy of ICIs given the positive correlation between GSDMB expression and MSI or TMB in these cancers." (PMID 32778143, 2020). "However, GSDMB plays other diverse non-pyroptotic functions in inflammatory pathologies and cancer." (PMID 36163066, 2022). "However, whether GSDMB has inherent oncogenic potential or affect cancer development and progression in vivo has not been tested yet in preclinical mouse models since mice lack GSDMB orthologue." (PMID 35281099, 2022). "Since GSDMB expression promotes cell survival to anti-HER2 treatment, the analysis of GSDMB gene status and/or GSDMB expression may lead to more precise molecular classification of this cancer subtype and, in turn, help to identify cases that may not benefit from the current therapies." (PMID 27462779, 2016). "For example, in bladder cancer, USP24 stabilizes the nonpyroptotic GSDMB isoform, which enhances STAT3 phosphorylation and promotes cancer cell proliferation." (PMID 37781519, 2023). "In addition to targeting the membrane of cancer cells, a new study showed that GSDMB exhibits direct microbiocidal activity through recognition of phospholipids found on gram-negative bacterial membranes, placing GSDMB as a center executioner of intracellular bacterial killing." (PMID 37134086, 2023). "Accordingly, we here prove that exon 6 translation is essential for GSDMB mediated pyroptosis, and therefore, GSDMB isoforms lacking this exon (GSDMB1-2) cannot provoke cancer cell death." (PMID 36899106, 2023). "GSDMB is located in the same chromosomal region than GSDMA; however, their expression is neither overlapping nor complementary during cancer development and progression." (PMID 24675552, 2014).
infection (7 papers, 2020 to 2025). The state of being infected such as from the introduction of a foreign agent such as serum, vaccine, antigenic substance or organism. "We demonstrate that porcine GSDMB (pGSDMB) is cleaved during infection to trigger pyroptotic cell death, thereby restricting the replication of porcine epidemic diarrhea virus (PEDV) and other swine enteric coronaviruses." (PMID 41410436, 2025). "Upon infection, IpaH7.8 recognizes and ubiquitinates GSDMB, thereby dampening the GSDMB-mediated bacterial lysis through proteasomal degradation of GSDMB23." (PMID 36599845, 2023). "The pyroptotic and bactericidal activity of GSDMB is a host response to infection by the bacterial pathogen Shigella flexneri, which employs the virulence effector IpaH7.8 to ubiquitinate and target GSDMB for proteasome-dependent degradation." (PMID 36599845, 2023). "A second role has been recently proposed for IpaH7.8 during infection: suppression of NK-cell-mediated killing of S. flexneri by ubiquitinating and targeting gasdermin B (GSDMB) for proteolytic destruction." (PMID 35887072, 2022). "Nonetheless, our findings suggest that both GSDMB and GSDME may play a role in pyroptosis of canine EICs induced by PSCs infection." (PMID 39679172, 2024). "Unlike GSDMD, GSDMB targets lipids enriched in bacterial membranes to directly form pores and lyse intracellular bacteria during infection." (PMID 35252199, 2022). "GSDMB is also not activated by caspases, but instead is activated by granzyme B released into epithelial cells by natural killer cells recruited to the site of infection." (PMID 35252199, 2022).
adenocarcinoma (3 papers, 2023 to 2024). A common cancer characterized by the presence of malignant glandular cells. "The rate of positive cytoplasmic GSDMB expression was relatively higher in adenocarcinoma NOS than in other histological types." (PMID 38711020, 2024).
bacterial infection (3 papers, 2023). "Considering the role of GSDMB in bacterial infection, recent studies provide evidence that bacteria have evolved mechanisms to shut down this Granzyme A driven mechanism of pyroptosis for immune evasion." (PMID 37266429, 2023).
immune diseases (2 papers, 2023 to 2025). "GSDMB, a unique member of the gasdermin family, which has the inability to form the pores in the cell membrane, and recently confirmed to be associated with immune diseases in humans." (PMID 38112597, 2023).
hematological malignancies (1 paper, 2011). "ACACA, RARA, NOTCH1 and NUP214 are known to form translocations in various types of hematological malignancies while many other fusion genes involve suspected oncogenes, such as RPS6KB1 (RPS6KB1-TMEM49 and RPS6KB1-SNF8), GSDMB (TATDN1-GSDMB) and MCF2L (LAMP1-MCF2L)." (PMID 21247443, 2011).
inflammation (1 paper, 2022). Aberrant reaction of the microcirculation characterized by movement of fluid and leukocytes from the blood into extravascular tissues. "However, insufficient research has explored the mechanisms by which GSDMB affects IBD, and it remains uncertain whether GSDMB-induced pyroptosis can contribute to the development of intestinal inflammation." (PMID 35677444, 2022).
peripheral neuropathies (1 paper, 2026). "The roles of GSDMA, GSDMB, and GSDMC in peripheral neuropathy remain largely unexplored, representing a significant knowledge gap." (PMID 41574659, 2026).
GSDMB also shares sentences with these, for which no sentence is quoted: allergic rhinitis (4 papers); lung carcinoma (4); ulcerative colitis (4); Allergy (3); liver cancer (3); Childhood onset (2); chronic rhinosinusitis (2); non-small cell lung carcinoma (2); Onset (2); primary biliary cholangitis (2); systemic sclerosis (2); acute lymphoblastic leukemia (1); Airway obstruction (1); ankylosing spondylitis (1); Arthritis (1); atopic asthma (1); atopic dermatitis (1); Behçet disease (1); bipolar disorder (1); bronchitis (1); cardiovascular disease (1); cervical squamous cell carcinoma (1); cervical squamous intraepithelial lesion (1); colon adenocarcinoma (1); coronary artery disease (1); COVID-19 (1); deafness, autosomal dominant 5 (1); gastrointestinal disease (1); hay fever (1); head and neck squamous cell carcinoma (1).
A further 16 diseases each share a sentence with GSDMB in 1 paper.